XIAP (X-linked inhibitor of apoptosis)
Diseases named in the same sentence as XIAP in open-access papers (continued):
Sharing a sentence is not in itself a finding about the gene and the disease.
protein deficiency (1 paper, 2017). "Nevertheless, HSCT in XIAP patients has been associated initially with bad prognosis compared with slam-associated protein deficiency and there are a limited number of studies concerning the outcomes of HSCT in patients with XIAP deficiency." (PMID 29312354, 2017).
psoriasis (1 paper, 2024). An autoimmune condition characterized by red, well-delineated plaques with silvery scales that are usually on the extensor surfaces and scalp. "Other cytokine therapies should be tested including anti-IL-17 and anti-IL-18 which are approved for use in other inflammatory conditions such as psoriasis and NLRC4/XIAP deficiencies respectively." (PMID 39132307, 2024).
pulmonary fibrosis (1 paper, 2013). Chronic progressive interstitial lung disorder characterized by the replacement of the lung tissue by connective tissue, leading to progressive dyspnea, respiratory failure, or right heart failure. "It would be informative to determine whether histone modifications are also responsible for altered expression of c-FLIP, survivin, or XIAP in pulmonary fibrosis." (PMID 23640463, 2013).
pulmonary hypertension (1 paper, 2021). Increased pressure within the pulmonary circulation due to lung or heart disorder. "The importance of this latter action of XIAP in pulmonary hypertension requires further investigation." (PMID 34068984, 2021).
retinal disease (1 paper, 2007). "Thus, targeting apoptosis through XIAP gene therapy may yield a general and widely applicable approach for these types of retinal disease." (PMID 17375200, 2007).
salivary gland tumor (1 paper, 2025). "The significant positive correlation observed between PHH3 and XIAP expression in our study highlights the potential complementary roles of these biomarkers in salivary gland tumor progression." (PMID 41253834, 2025).
Salmonella Infections (1 paper, 2022). Infections with bacteria of the genus SALMONELLA. "The dephosphorylation of XIAP blocks the activation of an apoptosis inhibitory pathway during Salmonella infection." (PMID 35846741, 2022).
sarcoidosis (1 paper, 2014). Sarcoidosis is a multisystemic disorder of unknown cause characterized by the formation of immune granulomas in involved organs. "To further explore XAF1 as a novel sarcoidosis candidate susceptibility gene in African Americans, we conducted IHC protein expression studies for both the XAF1 and X-linked inhibitor of apoptosis (XIAP) genes in granulomatous sarcoidosis-affected tissue." (PMID 24663488, 2014). "In IHC expression studies, we observed lack of XAF1 expression in sarcoidosis affected tissues and higher XIAP expression within sarcoid granulomas than in surrounding tissues." (PMID 24663488, 2014).
SARS-CoV infections (1 paper, 2022). "It was found that 45.87% of the associated genes (CASP3, CASP9, MAPK1, MAPK3, XIAP) contributed to cytochrome C-mediated apoptotic response and 3.67% of the associated genes (BECN1, FXYD2, GSK3B, HSP90AA1, ITGB1, MAP1LC3B) contributed to SARS-CoV infections." (PMID 36164436, 2022).
spinal muscular atrophy (1 paper, 2024). A motor neuron disease that affect the muscles, and characterized by muscle weakness and atrophy resulting from progressive degeneration and irreversible loss of the anterior horn cells in the spinal cord (i.e., lower motor neurons) and the brain stem nuclei. "In spinal muscular atrophy (SMA), neuron-specific IAP family members NAIP and XIAP effectively block the enzymatic activity of group II caspases (3 and 7) and reduce the expression levels of cleaved-caspase-3, thereby protecting spinal motor neurons (MNs) and preventing severe SMA." (PMID 39337436, 2024).
steatosis (1 paper, 2021). Increased lipid within the cytoplasm of cells. "As such, these results indicate that hepatocyte XIAP deletion does not aggravate liver injury, steatosis or inflammation in EtOH plus Jo2 mice model." (PMID 34025452, 2021).
thalassemia (1 paper, 2023). An inherited blood disorder characterized by a decreased synthesis of one of the polypeptide chains that form hemoglobin. "The 12-year-old XIAP-deficient patient exhibited approximately twice as many DDX4+ cells (patient 6) as the 9-year-old MDS patient and the 7-year-old ß-thalassemia major patient with the lower value." (PMID 36766757, 2023).
tongue squamous cell carcinoma (1 paper, 2025). A squamous cell carcinoma that arises from the tongue. "Further, the X-linked inhibitor of apoptosis protein expression significantly varies in OSCC originating from the floor of the mouth and tongue, with the expression being lower for tongue squamous cell carcinoma." (PMID 40144412, 2025).
cancer (526 papers, 2004 to 2026). A tumor composed of atypical neoplastic, often pleomorphic cells that invade other tissues. "In this study, we have identified LKB1 as a novel negative regulator of XIAP that can work even in MOMP-deficient cancer cells." (PMID 40544190, 2025). "XIAP functions as an inhibitor of apoptosis, and its upregulation has been associated with increased resistance to cell death in cancer cells, as demonstrated in previous studies." (PMID 40363754, 2025). "Given the critical role of XIAP in cancer cell survival and its association with chemoresistance, disrupting its interactions with caspases and other regulatory proteins presents a promising strategy for cancer therapy." (PMID 40076649, 2025). "By reducing MALAT1, betulinic acid enhances miRNA-22-3p activity, leading to downregulation of X-linked inhibitor of apoptosis protein (XIAP) and survivin, two proteins that support cancer cell survival." (PMID 41226811, 2025). "Particularly, we would like to briefly discuss the drug resistance caused by XIAP and survivin, which are the two most studied and play a leading role in conferring drug resistance in cancers." (PMID 40223934, 2025). "Endogenous Second mitochondria-derived activator of caspase (Smac) competes out the binding of caspases with XIAP and causes apoptosis, so that Smac mimetics are under clinical trials for anti-cancer chemotherapy." (PMID 40533441, 2025). "Overexpression of the X-linked inhibitor of apoptosis protein (XIAP) in many tumor cells has been reported as an adverse alteration that renders the cancer cell apoptosis-resistance capacity." (PMID 38529189, 2024). "IL-6 and IL-22, two cytokines that activate STAT3, enhanced XIAP in cancer cells, and such induction was attenuated in SMAD7-deficient cells." (PMID 39001432, 2024). "In these publications, the role of XIAP in cancer progression was intimately linked to the microenvironment." (PMID 36472768, 2023). "The scientists noted that emodin caused apoptosis and increased susceptibility of cancer cells to paclitaxel by down-regulating glycoprotein, X-linked inhibitor of apoptosis protein (XIAP), and surviving." (PMID 37720346, 2023). "Due to its key role in signal transduction pathways, deregulation of XIAP has been implicated in the pathogenesis of human cancers and inflammatory diseases." (PMID 35562367, 2022). "Expression of X-linked inhibitor of apoptosis (XIAP) is increased in BRCA1-mutated cancers and high levels are associated with improved patient outcomes after platinum chemotherapy." (PMID 35501389, 2022). "Caspases are directly or indirectly suppressed by inhibitor of apoptosis (IAP) family proteins (e.g., X-linked IAP [XIAP], cIAP1, and cIAP2), which are overexpressed in many human tumors and are thus promising targets for cancer therapy." (PMID 36553449, 2022). "More specifically, the X-linked inhibitor of apoptosis proteins (XIAP), is a potent negative regulator of the apoptotic pathways involving caspases-3, − 7 and − 9 blockade and thus promotes cancer cell survival via overexpression." (PMID 35279106, 2022). "The activation of JAK2 and the resulting dimerization of P-STAT3 regulate gene expressions, such as Bcl2, cyclinD, survivin, and XIAP, which causes cancer cell proliferation and resistance to anticancer drugs." (PMID 36500220, 2022).
cancer (continued). "For example, when USP11 is overexpressed, it can not only transform normal cells into cancer cells but also inhibit cell necrosis and apoptosis by stabilizing x-linked inhibitor of apoptosis protein (XIAP), thereby promoting the occurrence of tumors." (PMID 35359344, 2022). "X-linked inhibitor of apoptosis protein (XIAP) is an important anti-cancer drug target that binds to Hsp70 with an uncharacteristically tight affinity (~ 260 nM) in vitro." (PMID 35670950, 2022). "CD147 silencing also induces apoptosis through the inhibition of the X-linked inhibitor of apoptosis (XIAP) in multidrug-resistant cancer cells." (PMID 36012604, 2022). "There are many studies on XIAP (X-linked Inhibitor of apoptosis) as a target and prognostic biomarker in other cancer types." (PMID 34384473, 2021). "XIAP is atypically expressed in many human cancers and has been reported to cause drug resistance in the chemotherapy regimen." (PMID 34712428, 2021). "It is known that miR-133 regulates cancer cell apoptosis with suppression of caspase-9 whereas miR-24 enables cancer cells to survive by targeting X-linked inhibitor of apoptosis (XIAP) which suppresses apoptosis by downregulation of caspases." (PMID 33750303, 2021). "For example, the X-linked inhibitor of apoptosis protein (XIAP) is frequently upregulated in many cancer tissues and cells and has been recognized to be responsible for the cancer cell’s resistance to various apoptotic stimuli." (PMID 33916780, 2021). "X-linked inhibitor of apoptosis (XIAP) is responsible for anoikis resistance by inhibiting apoptotic cell death in cancer." (PMID 33435156, 2021). "Specifically, from dbMTS, we identified 23 candidate genes, two of which (BMPR1A and XIAP) were associated with diseases that increased the risk of cancer in patients." (PMID 32824926, 2020). "Actually, exosomal transfer of lncRNA-SBF2-AS1 into cancer cells represses the activity of miRNA-122-5p, thereby upregulating X-linked inhibitor of apoptosis protein (XIAP), a pro-survival factor." (PMID 32756339, 2020). "Dual down-regulation of both major anti-apoptotic proteins, XIAP and Bcl-2, has been reported to cause enhanced apoptosis, increased sensitivity to chemotherapy and can overcome resistance of cancer cells." (PMID 32587235, 2020). "X-linked inhibitor of apoptosis protein (XIAP) has been found to contribute to cancer growth and progression." (PMID 33126409, 2020). "Praziquantel was reported to inhibit cancer cell growth when used synergistically with paclitaxel via downregulating the expression of X-linked inhibitor of apoptosis protein (XIAP)." (PMID 32503412, 2020). "Many human cancers over-express B cell lymphoma 2 (Bcl-2) or X-linked inhibitor of apoptosis (IAP) proteins to evade cell death." (PMID 32587235, 2020). "On the other hand, high expression of XIAP is associated with paclitaxel resistance in OC, reducing its expression to promote apoptosis and increasing the sensitivity of drug-resistant cancer cells to paclitaxel." (PMID 32595416, 2020). "This study shows that OGT is a substrate of the E3 ubiquitin ligase X-linked inhibitor of apoptosis (XIAP) which plays an important role in cancer pathogenesis." (PMID 32994395, 2020). "Usually, XIAP has higher expression in cancer tissues than in normal tissues, whereas Smac has lower expression in cancer tissues than in normal tissues, both of which are associated with poor prognosis and survival rate of patients." (PMID 31699976, 2019). "A related strategy is the inhibition of X-linked Inhibitor of Apoptosis Proteins (XIAP), a family of proteins which block apoptosis by directly binding and inhibiting caspases, and which are frequently overexpressed in cancer cells." (PMID 31921698, 2019).
cancer (continued). "According to previous studies, XIAP plays a key role in many cancers and associated with poor prognosis." (PMID 31548877, 2019). "The X-linked inhibitor of apoptosis protein (XIAP) has been frequently shown to be upregulated in different cancer entities." (PMID 31151416, 2019). "Recent studies have shown a novel role of X-linked inhibitor of apoptosis protein (XIAP) in regulating the migration process of cancer cells and, therefore, linking to progression and poor prognosis of cancer." (PMID 31548877, 2019). "Among IAP family members, X-linked inhibitor of apoptosis protein (XIAP) is considered to be the most potent direct inhibitor of caspase activity and has become a strategic target to sensitize cancer cells to apoptosis stimulated by a number of regimens." (PMID 31248045, 2019). "X-linked inhibitor of apoptosis (XIAP)-associated factor 1 (XAF1) is a proapoptotic tumor suppressor that is frequently inactivated in multiple human cancers." (PMID 30042418, 2018). "The popular anti-cancer agents, doxorubicin and cisplatin, are associated with XIAP via protein kinase B (Akt)." (PMID 30513116, 2018). "Instead, FL118 inhibits the expression of multiple cancer-associated antiapoptotic proteins (survivin, Mcl-1, XIAP, cIAP2) in colon, prostate and ovarian cancer cells." (PMID 30285798, 2018). "Of the many members of the family, X-linked Inhibitor of Apoptosis Protein (XIAP) has been found to be the most promising target because XIAP is found to be over-expressed in a variety of cancers." (PMID 28893228, 2017). "AKT and XIAP are functionally associated with each other through a feedback mechanism in various cancer cells." (PMID 28704451, 2017). "Many studies have demonstrated that XIAP is a potential therapeutic target for cancer cells as overexpression of XIAP is found in many cancers and has been linked to the resistance to many therapeutic agents." (PMID 28704451, 2017). "The X-linked inhibitor of apoptosis protein (XIAP) is a well-known potent apoptosis suppressor and also participates in cancer cell biological behaviors, therefore attracting great attentions as a potential antineoplastic therapeutic target for past years." (PMID 28057023, 2017). "X-linked Inhibitor of Apoptosis (XIAP) has been shown to be over-expressed in various cancers leading to poor overall survival." (PMID 28893228, 2017). "The most characterized member is X-linked inhibitor of apoptosis protein (XIAP), which appears to be frequently deregulated in cancer." (PMID 26936767, 2016). "Other investigators have reported the association of XIAP overexpression with cancer progression, chemoresistance and poor prognosis in cancer patients." (PMID 27447744, 2016). "Elevated XIAP expression has been reported in a variety of human cancers and is associated with adverse tumor histology and decreased patient survival." (PMID 27259577, 2016). "Since XIAP amplifications are associated with cancers, we first examined the effect of the overexpression of this protein on the levels of the microtubule associated protein 1 light chain 3 (LC3-II), a well-established marker of autophagy." (PMID 25669656, 2015). "X-linked inhibitor of apoptosis protein is aberrantly expressed in a variety of human cancers and mediates resistance to chemotherapeutic drugs in specific subgroups of patients." (PMID 25120954, 2014). "TPEN killing of cancer cells was reported to be associated with degradation of the X-linked inhibitor of apoptosis (XIAP)." (PMID 25047035, 2014). "Our finding of an E2F-mediated increase of Cyclin E expression upon ectopic XIAPΔRING expression implicated XIAP as a cell cycle regulator in cancer cells." (PMID 25216527, 2014). "The inhibitor of apoptosis protein (IAP) member X-linked inhibitor of apoptosis protein (XIAP) is one culprit in the resistance to various apoptotic stimuli and frequently overexpressed in a number of different cancer types." (PMID 25120954, 2014).